IL6 (interleukin 6)
Diseases named in the same sentence as IL6 in open-access papers (continued):
Sharing a sentence is not in itself a finding about the gene and the disease.
tumor (continued). "Alternatively, CAF-secreted IL-6 and IL-8 may promote monocytes differentiation into M2 macrophages and further recruitment in the tumor to diminish natural killer (NK) cells cytotoxicity against CRC cells." (PMID 33553157, 2020). "In addition, higher cytokine release (in particular IL-1 and IL-6) leads to enhanced tumor development and increased pro-metastatic behavior." (PMID 33622996, 2020). "These macrophages now produced IL-6 and sIL-6R, which led to the outgrowth of the tumours." (PMID 32864098, 2020). "Third, tumor cells themselves increase the production of IL-6." (PMID 33351844, 2020). "Moreover, the adipose tissue adjacent to a growing tumor confers resistance of the tumor to radiotherapy by secreting IL-6, which upregulates Chk1 responsible for a radio-resistance phenotype." (PMID 32796696, 2020). "Along with the crosstalk between tumor plasma cells and BM niche cells, a high concentration of immunosuppressive factors including TGF-β, IL-10, IL-6, and prostaglandin E2 in the MM BM microenvironment promotes tumor propagation and survival and at the same time generates great immune dysfunction." (PMID 33194767, 2020). "IL-6, as an important cytokine, regulates various inflammatory factors which are responsible for inflammation, growth factors as well as angiogenic proteins which lead to tumor growth and metastasis." (PMID 31142737, 2019). "As IL-6 has also been shown to recruit mast cells to the tumor microenvironment, ZEB1-mediated IL-6 expression may explain the significant positive association we observed between ZEB1 expression and the abundance of intratumoral mast cells." (PMID 31780722, 2019). "Furthermore, phase II studies of combination therapy with Siltuximab have demonstrated anti-tumor effects for patients diagnosed with metastatic prostate cancer, suggesting clinical efficacy of targeting the IL-6-STAT signaling axis with combination therapies." (PMID 31684144, 2019). "Although we have not found any reports devoted to this relationship in the context of BCC, studies based on different neoplasia showed that IL-6 may upregulate Shh and Gli-1 expression." (PMID 31342143, 2019). "Thus, interfering with IL-6 signaling diminished myeloid immunosuppression, tumor growth, and increase mice survival." (PMID 32039024, 2019). "IL-6 was expressed in similar amounts in the bone marrow of all conditions examined: tumor-bearing mice injected with either MDA-MB-231GFP/Luc2 cells plus EO-231 cells (~ 27% of cells), MDA-MB-231GFP/Luc2 cells plus MC3T3-E1 cells (~ 40% of cells), or MDA-MB-231GFP/Luc2 cells alone (~ 27% of cells)." (PMID 30813947, 2019). "In addition, the inflammatory cytokine milieu can also effect T-cell recruitment by altering sensitivity towards selectins, increasing tumor vasculature as evidenced by increased IL-6 production and by inducing T-cell chemoattractants such as CCL5 and CXCL9." (PMID 31747946, 2019). "Moreover, the expression of IL-6 or IL-8 in tumour tissues was validated by immunohistochemistry to be positively correlated with tumour progression and poor survival, respectively." (PMID 31324197, 2019). "Depending on the tumor type, the RAS/MEK/ERK pathway acts alone or cooperates with other oncogenic pathways [e.g., JNK-, PI3K/AKT-, IL-6/STAT3, and echinoderm microtubule associated protein-like 4/anaplastic lymphoma kinase (EML4/ALK)-dependent pathways] in increasing PD-1L." (PMID 31117237, 2019). "In therapy-resistant stromal-tumor niches, IL-6/STAT3 signaling drives the expansion of BMSCs, that, in turn, secrete extracellular vesicles containing onco-miR221, able to induce hormonal therapy resistance through the generation of Notch3high/ERlow/CD133high CSCs." (PMID 30873026, 2019). "Moreover, the expression of the tumor-promoting cytokines IL-6, which has been shown to be regulated by IL-17C in different disease models, and CCL5 was decreased in lungs of IL-17C deficient Kras mice." (PMID 31316109, 2019).
tumor (continued). "Furthermore, inflammation induces the accumulation of immune cells such as “antitumor” M1 macrophages (producing ROSs, IL-1β, TNFα, IL-6, and IL-12) in the tumor microenvironment, which are then reprogrammed by the tumor cells to a M2 phenotype." (PMID 31662751, 2019). "Biofilms increase the production of interleukin 6 (IL6), suggesting that the gut microbiota may also induce the secretion of IL6 by the tumor." (PMID 31731747, 2019). "Furthermore, blocking IL-6 can counteract the differentiation and tumour-promoting effects of ADSCs." (PMID 31196220, 2019). "IL-6 and IL-2 levels appear to correlate with the BC patient outcome and could be considered in combination as putative tumor biomarkers as well as a prognostic marker for RT-induced toxicity (i.e., erythema and fatigue)." (PMID 30658426, 2019). "TGF-β and IL-6 have been reported to induce EMT in several tumor cell types." (PMID 30795783, 2019). "Furthermore, CAFs promote tumor progression through the release of interleukin-1 (IL-1), IL-6, IL-22, and IL-8, of which this latter plays a crucial role in hypoxia-induced tumor apoptosis resistance and EMT remodeling." (PMID 31484464, 2019). "Additionally, it has also been reported that the surrounding tumour microenverioment also promotes the appearance of new CSCs derived from non-stem cancerous cells by secreting several factors such as IL6, HGF or TGFβ-163." (PMID 31388092, 2019). "Therefore, we further measured the expression of IL-6 and TNFα in tumor tissues in mRNA level and found that the expression of IL-6 and TNF-α were higher in HCC-hMSCs group." (PMID 31142737, 2019). "CAFs produce most of the extracellular matrix, highly abundant in PDAC, but they also favor tumor growth and metastases by secreting inflammatory cytokines, mainly IL-6; chemokines; and chemokines ligands, namely CCL2 and C–X–C motif chemokine ligand 12 (CXCL12)." (PMID 30764482, 2019). "The chitinase family could induce the generation of pro- and anti-inflammatory cytokines and chemokines, such as interleukin (IL)-1β, IL-6, IL-12, and IL-13, making them potential modulators in an inflammatory tumor microenvironment." (PMID 31238895, 2019). "In an ovarian cancer model, tumor-driven Satb1 overexpression in terminally differentiated DCs results in a tolerant, pro-inflammatory state as evidenced by the secretion of Galectin-1 and IL-6, promoting tumor growth and immune evasion." (PMID 31921140, 2019). "Accordingly, we also detected an upregulation of IL-6 in Pan02 tumor-bearing mice." (PMID 31073508, 2019). "Furthermore, the expressions of MMP-2 and VEGF involved in metastasis, as well as inflammatory genes IL-1β, IL-6 and IL-10, showed dose-dependent decrease in tumor tissue after cisplatin exposure." (PMID 32257905, 2019). "IL-6 exhibits immune-suppressive effects on T cell-mediated anti-tumor immunity and is well known as a pivotal player in immunosuppressive states in tumor microenvironments, and in the development and metastasis of various cancers such as prostate and ovarian cancers." (PMID 31159449, 2019). "We showed that both chemokines (CXCL12, IP-10, and CCL27) and cytokines profiles (IL-1β and IL-6) were altered in the tumor microenvironment and might reduce NK cell function and recruitment to the tumor site." (PMID 31105699, 2019). "Moreover, in the tumor microenvironment, IL-6/JAK/STAT3 signaling acts to drive the proliferation, survival, invasiveness, and metastasis of tumor cells, while strongly suppressing the antitumor immune response." (PMID 31409327, 2019). "Previous studies have shown that TS stimulates IL-6 expression to promote tumor initiation." (PMID 31367260, 2019). "The IL-6/STAT3 signaling pathway is a classical inflammatory pathway involved in tumor formation." (PMID 30832202, 2019).
tumor (continued). "However, in human CRC tissues and CRC mouse models, IL-6 is produced mostly from activated myeloid cells in the tumor microenvironment, while IL-11 is produced mostly by cancer-associated fibroblasts (CAFs) and myeloid cells." (PMID 31754344, 2019). "Notably, both IL-8 and IL-6 tumor transcripts presented similar prognostic values (IL-8: hazard ratio (HR) = 1.28, 95% confidence interval (CI) = 1.12–1.45; IL-6: HR = 1.32, 95% CI = 1.16–1.5)." (PMID 31455042, 2019). "Two of the major pro-inflammatory cytokines secreted by senescent cells, IL-6 and IL-8, may function either to reinforce senescence or to promote tumor invasiveness." (PMID 30719231, 2019). "In PDAC patients, the elevated IL-6 levels found in serum, pancreatic juice and tissue, appear to predict tumor stage and survival, thus supporting the potential role of this cytokine as a malignancy predictor, but its sensitivity and specificity are extremely variable." (PMID 30764482, 2019). "Penetrance of tumor development could be further increased to 72% through an IL-6 dependent mechanism upon intraperitoneal injection of the biliary mitogen IL-33." (PMID 31769429, 2019). "Future studies combining targeting of IL-6 with therapies that induce apoptosis of WM cells, may prove to be effective; with IL-6 therapy slowing tumor growth and IgM secretion, and another therapy targeting the malignant cells." (PMID 31164961, 2019). "Furthermore, increased FIS-1 expression in cachectic skeletal muscle from tumor-bearing mice is dependent on IL-6; tumor-bearing mice treated with an IL-6 receptor antibody demonstrated an attenuation of muscle STAT3 and FIS-1 expression." (PMID 30918582, 2019). "Our results show that the primary tumour cells secreted abundant amounts of IL-6 and IL-8." (PMID 31324197, 2019). "In addition, recent studies have reported that inhibition of tumor CCRK or liver IL-6 increases interferon γ+ tumor necrosis factor-α+CD8+ T-cell infiltration and impaired tumorigenicity and is restored by recovery of MDSCs." (PMID 31464625, 2019). "Pleiotropic IL-6 role in tumor immunosuppression may be reasonably explained by interaction with other soluble factors." (PMID 31709183, 2019). "Additionally, it has been reported that IL-6 in primary tumours promotes tumour self-seeding, i.e., the re-colonisation of the tumour of origin by circulating tumour cells." (PMID 31010082, 2019). "Conversely, blockage of IL-6 reduces tumor burden and metastasis." (PMID 31590252, 2019). "Furthermore, when tumour-bearing DCs were co-cultured with cryo-thermal eosinophils, the expression level of pro-inflammatory cytokines (CXCL10, IL-1β, IL-15 and IL-6) was increased as compared to tumour-bearing DCs co-cultured with tumour-bearing eosinophils." (PMID 31519961, 2019). "It is recently shown that such resistance could be due to VEGF-mediated activation of IL-6 involving tumor microenvironment." (PMID 31075939, 2019). "Furthermore, IL-6 production by cancer cells has detrimental effects such as resistance to chemotherapeutics and eventual tumor relapse." (PMID 31174326, 2019). "It is well-known that the IL-6/STAT3/VEGFA axis plays a key role in tumor angiogenesis." (PMID 30886152, 2019). "However, at present one cannot rule out that CRP has no direct effect on tumors but rather displays a down-stream effect of IL-6 mediated tumor progression." (PMID 31788452, 2019). "Our results here suggest that inflammation in the tumor microenvironment may be instigated by multiple cytokines and that the highly-studied IL-6 may only be a limited part of the whole picture." (PMID 31007849, 2019). "Due to the IL-6 involvement in homeostasis, it is not surprising that its uncontrolled signaling is associated with pathological processes like tumor initiation, progression, and metastasis." (PMID 31191652, 2019).
tumor (continued). "A recent study reported that exosomes derived from heat-stressed tumor cells could induce the production of IL-6 by DCs and marcophage, which switches regulatory T cell into Th17 in tumor microenviroment in a HSP-70 dependent manner." (PMID 31647023, 2019). "In comparison, > 750-fold higher IL-6 was measured in sera from IRIS291 tumor-bearing mice injected with scrambled peptide (0.79 ± 0.09 ng/ml, upper left black) or IRIS293 tumor-bearing mice injected with scrambled peptide (0.76 ± 0.05 ng/ml, upper right black)." (PMID 31014367, 2019). "Tumor cells are also able to regulate the profile of the factors secreted by CAFs that stimulate cancer development; for example, interleukin-6 (IL-6) released from CAFs may modulate tumor angiogenesis." (PMID 31010006, 2019). "The tumor microenvironment provides favorable conditions for the enrichment of IL‐17‐producing γδ T cells, notably through enhanced levels of the cytokines IL‐1β, IL‐6, IL‐23 and IL‐7, which favor CD27− γδ T‐cell survival and promote IL‐17 expression." (PMID 31624593, 2019). "Our findings suggest that nevirapine significantly repressed migration and invasion/metastasis in WRO 82‐1 cells and tumor xenografts, which may be related to inhibition of IL‐6/STAT3 signaling pathway." (PMID 31631580, 2019). "Interleukin (IL6), a tumor promoting cytokine in various types of cancer including OSCC, may function as a central molecule in the proposed network." (PMID 30847302, 2019). "These soluble factors include Reg3 g, IL‐6, and IL‐10 in tumor‐conditioned medium." (PMID 30628173, 2019). "The splenic eosinophils in cryo-thermal-treated mice expressed high level of chemokines and pro-inflammatory cytokines (CCL5, CXCL10, IFN-γ, IL-6, IL-12 and IL-15), which could create immunostimulatory microenvironment contributing to anti-tumour immunity." (PMID 31519961, 2019). "It has been hypothesized that chemoattractant factors, released during radiotherapy by tumor cells, including granulocyte-macrophage colony stimulating factor (GM-CSF), IL-6, or IL-8, promote CTC recruitment back to the primary tumor site." (PMID 31185699, 2019). "Similarly to MM cells, also bone metastatic breast cancer cells expressing high levels of Jagged1 activate Notch signaling in OBLs, thus stimulating the secretion of IL-6 that, in turn, favors tumor growth and chemoresistance." (PMID 30873026, 2019). "Recently, tumor-secreted IL-6 has been reported to stimulate MDSCs generation and accumulation." (PMID 31534132, 2019). "Blockade of IL-6 expression significantly delayed the growth of MDA-MB-231-derived tumor." (PMID 31252615, 2019). "Then, IL-6 secreted by tumor or immune cells induces expressions of IDO1, such as IL-1β." (PMID 30708988, 2019). "IL-6 serum level positively correlated with tumor size (p = 0.005)." (PMID 31342143, 2019). "All these data seem to indicate that the non-expression of pro-inflammatory cytokines (such as IL-1β and IL-6), together with the expression of an anti-inflammatory cytokine (such as IL-10) could contribute to tumor immune escape." (PMID 31086100, 2019). "Therefore, we investigated the effect of ajoene extract on the level of myokines such as IL-6 and myostatin in muscles of tumor-bearing mice." (PMID 31717643, 2019). "MSCs are able to stimulate tumor growth, increase angiogenesis, and favor metastasis development mainly through the release of activating factors such as cytokines and growth factors including IL-6 and GDF15 in hematological malignancies." (PMID 31547627, 2019). "Tumor-secreted factors such as GM-CSF, IL-1β, IL-6, TGF-β, and TNF mediate expansion of MDSCs." (PMID 32039025, 2019). "To support the relevance of salivary IL-6 mRNA expression, we were looking for differences in salivary IL-6 protein concentrations of patients and controls and by detecting the expression of IL-6 protein in tumor cells and in tumor-infiltrating leukocytes (TIL)." (PMID 31766212, 2019).
tumor (continued). "To determine the effects IL-6 and IL-8 may have on anti-tumor immunity, we compared the frequency of circulating MDSC populations with the plasma concentration of IL-6 and IL-8." (PMID 31781510, 2019). "In addition, as reported by many authors curcumin also affects other molecular events implicated in the inflammation and the consequent promotion of tumor such as inflammatory cytokines (TNFα, interleukins IL‐1, IL‐6 and IL‐8)." (PMID 31313893, 2019). "Moreover, IL-1β and IL-6 are also elevated in the tumor-adipocyte microenvironment and interact with adipocytokines to aggravate tumor metastasis." (PMID 31500658, 2019). "Indeed, we and others have shown that in vitro tumor-conditioned tumor-associated macrophages (TAMs) exhibit a mixed M1/M2 macrophage phenotype, expressing both M2 (CD163 and CD206) and M1 (IL-1β, IL-6, TNF-α, and CCL3) markers." (PMID 30917934, 2019). "Paracrine IL-6 signalling between malignant cells and pro-tumour fibroblasts may thus be influential in the progression of DCIS to IDC." (PMID 31527531, 2019). "In addition to this physical effect, increased body temperature modifies the tumor vasculature by inducing IL-6 trans signaling, making the vasculature more permissible for cytotoxic T cell trafficking into the tumors." (PMID 31528182, 2019). "Next, to examine whether Bai could reprogram macrophages toward an M1-like phenotype, leading to tumor suppression, we measured the presence of IL-6 and TNF-α in the supernatant of RAW264.7 cells following treatment with Bai." (PMID 31777307, 2019). "However, during trans signaling, the major signaling pathway used within the tumor microenvironment and CNS, IL-6 binds in solution to a soluble Il-6 receptor (sIL-6R) which is secreted by cells." (PMID 31174326, 2019). "In the majority of cases, tumor cells, and TILs were positive for IL-6 staining." (PMID 31766212, 2019). "IL-6 can either inhibit or promote tumor cell growth in a cell type- and context-dependent manner." (PMID 31557902, 2019). "IL-6 secreted by MSCs not only regulates tumor cells’ cEMT, but also induces the chemoresistance." (PMID 31130595, 2019). "Published data indicate that IL-6 or IL-17A acts as a pro-tumor factor in MCL or DLBCL." (PMID 30755239, 2019). "Tumor microenvironment inflammatory cells (e.g., immune cells, fibroblasts, and endothelial cells), but also cancer cells, are known to produce and secrete several cytokines, such as IL-6, IL-10, IL-13, VEGF, and TGFβ." (PMID 30764482, 2019). "High levels of IL-6 in the TME of MCL promote tumor growth and induce drug-resistance." (PMID 30755239, 2019). "It was speculated that the concept of non-cell-autonomous STAT3 activation of tumor cells brought about by IL-6 trans-signaling was a general phenomenon, which might also be applied to other neoplasias and cancer diseases." (PMID 31694340, 2019). "Moreover, in a PDAC mouse model, the tumor stroma was found to produce high levels of IL-6, whereas the tumor expressed high levels of PD-L1." (PMID 31847096, 2019). "IL-6 produced by the microenvironment within TNBC tumors enhances tumor growth and metastasis." (PMID 31014367, 2019). "Immune cells secrete the pro-inflammatory cytokine IL-6, which mediates the invasiveness of tumor cells in an in vitro coculture model of colorectal cancer, thereby stimulating the secretion of miR-21 and miR-29b from tumor cells." (PMID 31766495, 2019). "In addition, IL-6 promotes the proliferation and survival of tumor cells, as well as angiogenesis, by regulating Janus kinase (JAK)/STAT3 signaling pathways." (PMID 31500658, 2019). "IL-6 acts both intrinsically on tumor cells and extrinsically on tumor-associated cells within the complex TME to support cancer cell proliferation, survival, angiogenesis, and tumor evasion of immune surveillance." (PMID 31557902, 2019). "This highlights the direct effect of IL‐6 on promoting tumor progression." (PMID 31609088, 2019).